HILPDA (hypoxia inducible lipid droplet associated)
Description:
Increases intracellular lipid accumulation. Stimulates expression of cytokines including IL6, MIF and VEGFA. Enhances cell growth and proliferation.
Synonyms: C7orf68; HIG2; FLJ21076; HIG-2
Tractability: Antibody: UniProt places it where antibodies can reach, with medium confidence; UniProt predicts a signal peptide or a membrane-spanning region; its Gene Ontology location is reachable by antibodies, with medium confidence. PROTAC: ubiquitination databases record sites on it.
Gene: Protein-coding gene on chromosome 7 (128,455,829 to 128,458,423, forward strand). Ensembl gene ENSG00000135245.
Subcellular location: Lipid droplet; Secreted; Membrane
Subcellular location (Human Protein Atlas): Lipid droplets; Nucleoplasm
Pathways (Reactome):
Metabolism: Lipid particle organization
Gene Ontology:
Molecular function: protein binding; signaling receptor binding; lipid transfer activity
Biological process: autocrine signaling; cellular response to hypoxia; positive regulation of cell population proliferation; positive regulation of cytokine production; positive regulation of lipid storage; lipid droplet organization; intermembrane lipid transfer
Cellular component: cell surface; extracellular region; lipid droplet; secretory granule; cytosol; membrane
Genetic constraint (gnomAD): Loss-of-function variants: 1 observed, 1.78 expected, observed/expected ratio (o/e) 0.56, 90% interval 0.18 to 1.79. That is too few expected variants to judge how well the gene tolerates losing a copy. Missense variants: 72 observed, 78.04 expected, observed/expected ratio (o/e) 0.92, 90% interval 0.76 to 1.12. Synonymous variants: 37 observed, 35.41 expected, observed/expected ratio (o/e) 1.04, 90% interval 0.8 to 1.38.
Homologues: Orthologues: chimpanzee HILPDA (100% identical), rabbit HILPDA (79% identical), mouse Hilpda (78% identical), guinea pig HILPDA (73% identical), rat Hilpda (73% identical).
Diseases named in the same sentence as HILPDA in open-access papers:
HILPDA is named in the same sentence as 52 diseases in open-access papers, as found by Europe PMC text mining. Sharing a sentence is not in itself a finding about the gene and the disease. The quoted sentences say what the papers report.
clear cell carcinoma (9 papers, 2020 to 2024). "In contrast, EPAS1 upregulates hypoxia-induced lipid droplet-associated proteins (HILPDA/HIG2) in clear-cell carcinoma cells, promoting ferroptosis through lipid peroxidation and increased PUFAs synthesis." (PMID 39737174, 2024). "EPAS1 promotes ferroptosis in clear cell carcinoma by upregulating hypoxia‐induced lipid droplet‐associated (HILPDA/HIG2)." (PMID 38722283, 2024). "The ferroptosis-sensitizing effect of HIF-2α was also observed in clear cell carcinomas, where HIF-2α selectively enriches polyunsaturated lipids via upregulation of the hypoxia-inducible lipid droplet-associated protein (HILPDA)." (PMID 39372215, 2024). "The HIF-2α-HILPDA (hypoxia-inducible, lipid droplet-associated protein) axis also promotes ferroptosis by enriching PUFA lipids, the rate-limiting substrates for lipid peroxidation in clear-cell carcinoma cells." (PMID 39056735, 2024). "Increased lipid unsaturation might correlate with HILPDA activation as HIF1α/2α was shown to significantly enrich polyunsaturated lipids via HILPDA in clear-cell carcinomas, independent of its ATGL-suppressing function." (PMID 34277635, 2021).
renal cell carcinoma (9 papers, 2014 to 2022). "In various cancer cells including renal cell carcinoma, ovarian clear cell carcinoma, colorectal adenoma and carcinoma, upregulation of HILPDA has been observed." (PMID 34078402, 2021). "In renal cell carcinoma (RCC), hypoxia induces EPAS1 activation and up-regulates the expression of HILPDA to promote PUFAs production and subsequent lipid peroxidation, and induce ferroptosis." (PMID 34996454, 2022).
glioma (5 papers, 2011 to 2023). A benign or malignant brain and spinal cord tumor that arises from glial cells (astrocytes, oligodendrocytes, ependymal cells). "Out of these NRGs, 19 NRGs (EGLN3, HILPDA, HMBS, HYOU1, BNIP3, etc.)were found to be enriched in glioma tissues while 13 genes (SLC4A1, IL6, EPAS1, ACE, HMOX1, etc.)were decreased compared to normal tissues." (PMID 37934582, 2023). "Hypoxia-inducible protein 2 (HIG2, also known as HILPDA) is highly expressed in tumors, including gliomas, and correlates with tumor grade and poor patient prognosis." (PMID 36233088, 2022).
clear cell renal cell carcinoma (4 papers, 2021 to 2026). "In clear cell renal cell carcinoma cells, hypoxia-inducible factor 2 alpha (HIF-2α) regulates the expression of hypoxia-inducible lipid droplet-associated protein (HILPDA)." (PMID 41513612, 2026). "In renal clear-cell carcinomas (CCCs), HIF-2α selectively enhances PUFA-phospholipids, which are sensitive to reactive oxygen species (ROS), by overexpressing hypoxia-inducible lipid droplet-associated protein (HILPDA)." (PMID 38540154, 2024). "For example, in renal clear cell carcinomas, which are characterized by aberrant lipid and glycogen accumulation, it was found that hypoxia-inducible factor 2 alpha (HIF2-α) can drive the production of PUFAs, through the activity of hypoxia-inducible, lipid droplet-associated protein (HILPDA)." (PMID 33499222, 2021).
hepatocellular carcinoma (4 papers, 2019 to 2024). A malignant tumor that arises from hepatocytes. "Levels of HILPDA were markedly induced by fatty acids in several hepatoma cell lines." (PMID 33465519, 2021). "•HILPDA expression is induced by fatty acids in hepatoma cells." (PMID 33465519, 2021). "While hypoxia inducible lipid droplet-associated (HILPDA) is strongly connected with poor mortality in patients with MASH-driven HC, it has also been observed to support the formation of 3D epithelial spheroids and the viability of human hepatoma cells under anoxic culture conditions." (PMID 38818407, 2024).
cervical carcinoma (3 papers, 2005 to 2019). A carcinoma arising from either the exocervical squamous epithelium or the endocervical glandular epithelium. "Initially, HILPDA was identified in cervical cancer cells with activation under hypoxic conditions, which is why it was first termed hypoxia induced protein 2 (HIG2)." (PMID 30884788, 2019).
fatty liver disease (2 papers, 2018 to 2023). A reversible condition wherein large vacuoles of triglyceride fat accumulate in liver cells via the process of steatosis. "Thus, HILPDA could also provide new therapeutic directions for metabolism‐related fatty liver disease as well as T2DM in the future." (PMID 37904700, 2023).
liver cancer (2 papers, 2021 to 2022). An epithelial or non-epithelial malignant neoplasm that arises from the liver. "The results revealed that HILPDA was highly expressed in liver cancer tissues." (PMID 33816230, 2021).
mantle cell lymphoma (2 papers, 2010 to 2021). Mantle cell lymphoma is a rare form of malignant non-Hodgkin lymphoma affecting B lymphocytes in the lymph nodes in a region called the ``mantle zone''. "Previous studies have shown the oncogenic role of HILPDA in head and neck carcinoma, neuroblastoma, and mantle cell lymphoma amongst others." (PMID 33816230, 2021).
non-alcoholic fatty liver disease (2 papers, 2018 to 2021). "If the expression level of HILPDA in human liver is sufficiently high, inactivation of HILPDA could in theory be a promising strategy to treat non-alcoholic fatty liver disease." (PMID 33465519, 2021).
non-alcoholic steatohepatitis (2 papers, 2021 to 2023). "Hepatocyte-specific deficiency of HILPDA in mice modestly but significantly reduced hepatic triglycerides in mice with non-alcoholic steatohepatitis." (PMID 33465519, 2021).
Obesity (2 papers, 2019 to 2023). Accumulation of substantial excess body fat. "Mechanistic studies are needed to investigate whether proteins such as SFRP2, HILPDA, and SCD mediate associations between obesity and its comorbidities." (PMID 30884788, 2019).
preeclampsia (2 papers, 2016 to 2025). Preeclampsia is a hypertensive disorder of pregnancy that is characterized by new-onset hypertension with proteinuria presenting after 20 weeks of gestation, and depending on mild or severe forms may initially present with severe headache, visual disturbances, and hyperreflexia. "Interestingly and in accordance with the role of hypoxia in preeclampsia, HIF1A can regulate the expression of several top DEGs identified in the meta-analysis including: LEP, FLT1, INHA, BHLHE40, SPAG4, HK2, HILPDA and ERO1L." (PMID 27802351, 2016).
Adrenocortical Carcinoma (1 paper, 2021). "In addition, the expression of HILPDA was closely related to the clinical stage, being higher in patients with relatively high stages of several tumor types, including Adrenocortical Carcinoma (ACC), HNSC, Kidney Chromophobe (KICH), and LIHC." (PMID 33816230, 2021).
brain tumors (1 paper, 2021). "This was accompanied by regionally restricted upregulation of hypoxia-inducible lipid droplet-associated (HILPDA) gene expression in organoid cores and pseudopalisading regions of clinical GBM specimens, but not lower-grade brain tumors." (PMID 34059134, 2021).
breast carcinoma (1 paper, 2024). "Interestingly, lipid-accumulating lung mesenchymal cells promote the metastasis of breast cancer cells by metabolic rewiring of cancer cells and natural killer cells, partially via the IL-1β-HILPDA-ATGL axis." (PMID 38736892, 2024).
colon cancer (1 paper, 2025). "Mechanistically, KynA downregulates the expression of P4HA2 to promote the ubiquitination and degradation of HIF-1α, which leads to a decrease in the transcription of HILPDA, and ultimately leads to an increase in lipolysis of colon cancer cells." (PMID 39920992, 2025). "In conclusion, our results validate the role of the KynA/P4HA2/VHL/HIF-1α/HILPDA axis in promoting colon cancer progression due to sleep deprivation." (PMID 39920992, 2025). "In conclusion, our results validate the role of the P4HA2/HIF-1α/HILPDA signaling axis in promoting colon cancer progression." (PMID 39920992, 2025). "To investigate the presence of KynA/P4HA2/VHL/HIF-1α/HILPDA axis in mediating the effects of sleep deprivation on colon cancer, we underwent rescue experiments." (PMID 39920992, 2025). "The results of Transwell assays and wound healing assays showed that knockdown of HILPDA inhibited the migration of colon cancer cells." (PMID 39920992, 2025). "Then, the results of CCK-8 assays and colony formation assays showed that knockdown of HILPDA inhibited the proliferation of colon cancer cells." (PMID 39920992, 2025). "In conclusion, our results suggest that KynA inhibits colon cancer progression by downregulating HILPDA to remodel lipid metabolism." (PMID 39920992, 2025). "To determine if HILPDA is a key molecule in KynA-mediated lipid metabolism reprogramming, we constructed a HILPDA gene overexpression plasmid and transfected it into colon cancer cells." (PMID 39920992, 2025). "Similarly, the impact of the KynA/P4HA2/HILPDA axis on colon cancer cell proliferation and migration was confirmed." (PMID 39920992, 2025). "Furthermore, we used GEO dataset GSE10950 and tissue chips to assess P4HA2/VHL/HIF-1α/HILPDA signaling axis on colon cancer." (PMID 39920992, 2025). "Additionally, CCK-8 assays, colony formation assays, wound healing assays, Transwell assays, and WB demonstrated that HILPDA overexpression reversed KynA’s inhibitory effects on colon cancer cells." (PMID 39920992, 2025). "However, it remains unclear whether KynA regulates lipid metabolism reprogramming in colon cancer cells through HILPDA." (PMID 39920992, 2025). "Results indicated that HILPDA overexpression counteracted the increase in ATGL activity induced by KynA, leading to increased lipid accumulation in colon cancer cells." (PMID 39920992, 2025).
ischemic heart disease (1 paper, 2023). "HILPDA regulates lipid storage, and is known to be induced in atherosclerotic plaques, where it augments atherosclerotic inflammation and drives inflammation in ischemic heart disease." (PMID 37753073, 2023).
pancreatic cancer (1 paper, 2021). "Among 39 differentially expressed factors, seven up-regulated genes (CAV2, CIDEC, HILPDA, HSD17B11, NCEH1, RAB5A, and SQLE) and two down-regulation genes (BSCL2 and FITM1) were significantly associated with overall survival of pancreatic cancer patients." (PMID 34078402, 2021). "We further identified that enhanced expression of 7 genes namely CAV2, CIDEC, HILPDA, HSD17B11, NCEH1, RAB5A, and SQLE are associated with significantly shorter overall survival whereas elevated expression of BSCL2 and FITM1 correlates with longer overall survival of pancreatic cancer patients." (PMID 34078402, 2021). "Overexpression of HILPDA, but not DGAT1/2, is associated with shorter overall survival in pancreatic cancer patients, suggesting that additional roles of HILPDA, other than regulating triacylglyceride (TAG) synthesis, may influence the outcome of pancreatic cancer patients." (PMID 34078402, 2021).
renal carcinoma (1 paper, 2022). A carcinoma arising from the epithelium of the renal parenchyma or the renal pelvis. "Moreover, we proved that two lipid regulatory genes HILPDA and PLIN2, important for ferroptosis sensitization in renal cancers, were significantly upregulated following RXD treatment and the upregulation was merely HIF-2α-dependent." (PMID 36209275, 2022).
uterine cancer (1 paper, 2022). Primary or metastatic malignant neoplasm involving the uterine corpus and/or the cervix. "Gene expression analysis shows that hypoxia-inducible lipid droplet associated (HILPDA), one of the LD-associated proteins, is highly expressed in bladder, colon, kidney, lung, pancreas, and uterine cancers as well as in GBM." (PMID 36009491, 2022).
cancer (36 papers, 2005 to 2025). A tumor composed of atypical neoplastic, often pleomorphic cells that invade other tissues. "HIF-1 induces HIG2/HILPDA (hypoxia-inducible protein 2/hypoxia-inducible lipid droplet associated) expression, encouraging lipid aggregation in both cancer and normal cells storage." (PMID 38399410, 2024). "Here, HIF-2α selectively augments the cancer cell membrane’s lipid composition with PUFAs by inducing the hypoxia-inducible lipid droplet-associated protein (HILPDA) gene." (PMID 38217037, 2024). "We further verified the cancer promotion function of pivotal genes HILPDA and MUC1 and revealed the probable association between them and ferroptosis." (PMID 36439512, 2022). "Studies in HILPDA-deficient macrophages and cancer cells have firmly established the physiological relevance of ATGL inhibition by HILPDA [18,]." (PMID 33465519, 2021). "In our study, we examined HILPDA expression levels and prognostic function in pan-cancer data using TCGA data from UCSC Xena." (PMID 33816230, 2021). "While we do not provide a mechanistic explanation for this observation, a recent study has found that increased HILPDA expression enriches cancer cells in polyunsaturated fatty acid‐containing triglycerides." (PMID 33484195, 2021). "For example, HILPDA is overexpressed in colorectal cancer and promotes cancer progression via hypoxia-dependent and independent pathways." (PMID 33816230, 2021). "HILPDA exerted an oncogenic function by neutralizing the tumor suppressive role of ATGL under hypoxic conditions, whereas disruption of ATGL and/or HILPDA incurred little changes for cancer cell growth under normoxia." (PMID 30367950, 2019). "Hypoxia-inducible protein 2 (HIG2), also known as HILPDA (hypoxia inducible lipid droplet associated), was identified as a hypoxia-induced gene in several tissues and cancers." (PMID 27329597, 2016). "It has been reported that lung mesenchymal cells in the pre-metastatic niche induce an increase of lipids storage in neutrophils through the PGE2- HIF1α–HILPDA axis, and those neutrophils promote the growth of disseminated cancer cells by feeding them lipids during the early stage of colonization." (PMID 37174093, 2023). "In addition, HIF-1 increases lipid accumulation in both cancer and normal cells by induction of HIG2/HILPDA (hypoxia-inducible protein 2/hypoxia-inducible lipid droplet-associated)." (PMID 34071836, 2021). "We first assessed HILPDA expression in pan-cancer data from TCGA." (PMID 33816230, 2021). "Because HILPDA is strongly induced under hypoxic conditions, it is conceivable that it regulates lipolysis, particularly under hypoxic or anaerobic conditions as often observed in rapidly growing malignant tumors." (PMID 29326160, 2018). "Additionally, HILPDA is abundantly expressed in many cancer tissues and atherosclerotic plaques." (PMID 29326160, 2018). "Interestingly, HILPDA is one of the top upregulated genes in neutrophils treated by c-Met high CM, suggesting that c-Met high cells might also stimulate neutrophils to provide lipids for cancer cells in the brain." (PMID 37174093, 2023). "Our risk model can predict OS survival outcomes, and we propose that HILPDA and MUC1 are potential targets for cancer therapy." (PMID 36439512, 2022). "We further analyzed the relationship of HILPDA with TMB and immunosuppressive genes using TCGA pan-cancer data." (PMID 33816230, 2021). "In accordance with these findings, we found an increased expression of PLIN2 and HILPDA, and reduced levels of CPT1A transcripts in cancer tissue." (PMID 33322148, 2020). "Our results are particularly intriguing, because the functional involvement of HILPDA in cancer-related WNT-signaling and the potential use of this molecule as a novel therapeutic target for cancer treatment is under discussion." (PMID 30884788, 2019).
cancer (continued). "While three of the chimeras (ACTB->POTEM, ACTB->POTEE and SP100->HMGB1) have been found in normal population, three of the chimeras (C2orf27A->NBEA, HILPDA->EFCAB3, FARSB->TRIM61) were previously identified only in cancer samples." (PMID 25133550, 2014). "We also identified the top 1 GEAR in individual cancer types, such as TLL1 (BLCA), PGK1 (BRCA), RFXANK (CESC), DPP7 (COAD), VWA8 (KIRC), SCMH1 (LGG), HILPDA (LIHC), TLE1 (LUAD), CD151 (LUSC), ANKRD13A (OV), SOCS2 (PAAD), DRG2 (PRAD), ADAMTS6 (STAD), PSMB8 (THCA), ASS1 (UCEC)." (PMID 41404730, 2025). "Moreover, a recent study proposed that HILPDA but not G0S2 downregulated ATGL activity of hypoxic cancer cells." (PMID 30367950, 2019). "In addition, PPARα can target the regulatory region of the HILPDA gene to enhance TAG storage in hepatocytes, although this PPAR-HIG2 axis has not been demonstrated in cancer cells (route 17)." (PMID 27589734, 2016).